NFKBIA (NFKB inhibitor alpha)
Diseases named in the same sentence as NFKBIA in open-access papers (continued):
Sharing a sentence is not in itself a finding about the gene and the disease.
prostate carcinoma (28 papers, 2003 to 2025). A carcinoma that arises from epithelial cells of the prostate gland. "Curcumin was reported to increase the susceptibility of prostate cancer LNCaP cells to TNFRSF10A by inhibiting NFKB stimulation through hindering phosphorylation of NFKBIA/IκBα and its degradation." (PMID 36497321, 2022). "We aimed to examine the association between PPARG Pro12Ala, NFKB1 -94 ins/del, NFKBIA -826C/T, COX-1 (50C>T), and COX-2 (-1195G>A) polymorphisms on prostate cancer risk." (PMID 26788504, 2015). "The effect of interactions between polymorphisms in related genes (NFKB1 and NFKBIA; COX-2 and COX-1) on the risk of prostate cancer was also examined." (PMID 26788504, 2015). "Similarly, in prostate cancer, cells with stem-like characteristics demonstrated increased NF-κB activity related to a decrease in NFKBIA transcription and IκBα levels." (PMID 30200302, 2018). "In this study, we investigated and established the association of five inflammation-related genetic polymorphisms, namely, PPARG Pro12Ala, NFKB1-94 ins/del, NFKBIA-826C/T, COX-1 (50C>T), and COX-2 (-1195G>A) polymorphisms, with prostate cancer risk in a Chinese population." (PMID 26788504, 2015). "Through expression profiling and functional studies, we identified NFKBIA (IκBα) as a critical mediator of this therapy, and in doing so provided novel insight into AR signaling and how this might be effectively targeted in prostate cancer." (PMID 26907477, 2016). "This hypothesis is supported by the observation that knockdown of NFKBIA in the absence of drug treatment resulted in a similar level of cell death to that observed with the combination in two independent prostate cancer cell lines." (PMID 26907477, 2016).
colon carcinoma (26 papers, 2008 to 2023). "In the present study, we found that the genetic variant, rs696 A>G of the NFKBIA gene significantly correlates with colon cancer in Iranian population." (PMID 29564065, 2018). "We believe this work would further justify the role of NFKB1/NFKBIA axis in colon cancer susceptibility." (PMID 29564065, 2018).
melanoma (26 papers, 2005 to 2023). A malignant, usually aggressive tumor composed of atypical, neoplastic melanocytes. "Other studies showed that NFKBIA was also upregulated in six human malignant melanoma cell lines after carbon ion exposure (290 MeV/n, LET 50 keV/μm)." (PMID 30061500, 2018). "Increased cellular expression of Chk1 and IκBα was not due to higher CHEK1 and NFKBIA mRNA transcripts, again consistent with CMA disruption in melanoma cells with high LAMP-2C expression." (PMID 30211163, 2018).
hepatocellular carcinoma (24 papers, 2012 to 2025). A malignant tumor that arises from hepatocytes. "Next, we orthogonally validated the observed protective phenotypes of inactivated NFKBIA, EIF4E2, and EIF4H by generating knockout lines from Huh7.5.1 (hepatocellular carcinoma) cells ectopically expressing ACE2 and TMPRSS2." (PMID 37803001, 2023).
asthma (23 papers, 2006 to 2026). "NFKBIA/IκBα is identified to be a central hub in transcriptional responses of prevalent childhood lung diseases, including asthma." (PMID 24790987, 2014). "NFKBIA (IκBα) tightly regulates the activity of NFκB with the modulation of NFKBIA regarded as an anti-inflammatory and immunosuppressive mechanism in asthma." (PMID 24983946, 2014). "First, SARS-CoV-2 infection might alter the expression of several key inflammatory genes: IRAK3, which is associated with asthma; ADRB2, which is an essential genetic factor for asthma; and NFKBIA, which shows critical transcriptional responses in childhood asthma." (PMID 33156843, 2020).
psoriasis (23 papers, 2013 to 2025). An autoimmune condition characterized by red, well-delineated plaques with silvery scales that are usually on the extensor surfaces and scalp. "The target proteins of these active compounds, including IL1B, TNF, STAT3, IL6, NOS2, and NFKBIA, were found to be directly associated with psoriasis-related disease proteins." (PMID 39590306, 2024). "In 2010, two GWAS established the association of two NFKBIA SNPs and the risk of psoriasis, while in 2015 a third GWAS confirmed the association of an additional SNP with psoriasis." (PMID 34884808, 2021). "Recently, genome-wide association studies (GWAS) have found a significant association between psoriasis and single-nucleotide polymorphisms (SNPs) within NFKB1, NFKBIA, and NFKBIZ." (PMID 31815120, 2019). "We investigated the association between three common variants in NFKB1 (rs230526), NFKBIA (rs7152376), and NFKBIZ (rs3217713 indel) and the risk of developing psoriasis/PsA or their main clinical outcomes." (PMID 31815120, 2019). "Several recently identified single-nucleotide polymorphisms (SNPs) that are linked to psoriasis susceptibility are found adjacent or in close proximity to genes associated with the innate immune response, such as IFIH1 (MDA5), NFKBIA, STAT3, and SOCS1." (PMID 25658361, 2015). "NFKBIA was identified as a potential target due to its ability to inhibit NF-κB activity, which regulates NF-κB-mediated inflammatory responses and cell proliferation, making it effective in psoriasis treatment." (PMID 39590306, 2024). "Along the same lines, a simplified version of the cAMP-signaling KEGG pathway focusing on the signal transduction relevant to psoriasis was created, and its analysis revealed SNPs within CBP, ATF1 and NFKBIA genes to be associated with the response to apremilast." (PMID 38540428, 2024). "When taken together with genes (that is, TNIP1, TNFAIP3 and NFKBIA) mapping to known psoriasis loci that are well-appreciated as components of NF-κB signalling, our results further implicate this pathway in the pathophysiology of psoriasis." (PMID 28537254, 2017). "In a recent study, miR-378a ectopic overexpression, mimicking the miRNA increase in psoriasis, was found to promote p63 transport to the nucleus and further contributed to the IL-17A-mediated activation of NF-κB pathway signaling by acting as suppressor of NFKBIA." (PMID 36174034, 2022). "The analysis demonstrated that schizandrin II directly influenced psoriasis-related proteins such as IL-4, IL-6, STAT3, and NFKBIA, while schizandrin A modulated the NFKBIA protein." (PMID 39590306, 2024). "Overexpression of CHUK, IKBKB, NFKBIA, NFKB1, JAK2, STAT1 and STAT3, as inflammation related factors, was detected in the psoriasis model group." (PMID 34834106, 2021). "Furthermore, α-humulene and torilin from Cnidi fructus were identified as targeting psoriasis-related proteins, including IL1B, TNF, NOS2, and NFKBIA." (PMID 39590306, 2024). "Increasing evidence indicates that genetic mutations in genes such as TNFAIP3, TNIP1, NFKBIA, TRAF3IP2, and CARD14 result in an impaired negative regulation of NF‐κB proinflammatory activity leading to psoriasis." (PMID 28377495, 2017).
diabetes (22 papers, 2011 to 2022). "Several other genes displaying inverted correlations have previously been linked to diabetes (7/18), either by functional studies (TRIB1, glucose metabolism; NFKBIA, insulin resistance pathway) or as candidate disease genes in GWAS or gene expression studies (TMPPE, PRTG, and ZNF319)." (PMID 31159854, 2019). "Moreover, we performed a subpopulation analysis to investigate the gene-environmental interaction between NFKBIA -826C/T polymorphism and some CAD risk factors such as hypertension, smoking and diabetes." (PMID 29911119, 2018).
Immunodeficiency (22 papers, 2009 to 2025). Failure of the immune system to protect the body adequately from infection, due to the absence or insufficiency of some component process or substance. "NFKBIA mutations promote the formation of IL-1β, and give rise to severe immune deficiency in liver diseases." (PMID 37056763, 2023). "For instance, a patient with a missense mutation of NFKBIA, which results in the L34P IkB-alpha variant, concurrently exhibited symptoms of both autoinflammatory disease and immunodeficiency." (PMID 37876023, 2023). "In conclusion, whole-exome sequencing identified a novel NFKBIA Ser32Cys mutation in a patient exhibiting mild features of ED with immunodeficiency." (PMID 36292785, 2022). "The patients with Ser32Ile, Ser32Gly, Ser32Arg, and Ser32Asn mutation in NFKBIA manifested features of EDA with immunodeficiency." (PMID 36292785, 2022). "In the first of these, ectodermal dysplasia with immunodeficiency, a c.40G>T mutation in NFKBIA, the gene encoding IκB-α, results in a deletion of the N terminus of the IκB-α and production of a 31 kD form of IκB-α." (PMID 32781504, 2020). "An overlapping clinical syndrome with autosomal dominant inheritance causing ectodermal dysplasia and immunodeficiency is caused by mutations in NFKBIA encoding IκBα, part of the inhibitory complex." (PMID 20180797, 2010). "Another study showed that a novel NFKBIA variant caused immunodeficiency, manifested in JIA." (PMID 37445800, 2023). "In addition, variants in the gene that code for NFKBIA are associated with various forms of ectodermal dysplasia with immunodeficiency." (PMID 30116248, 2018). "Additionally, variants in the gene that code for NFKBIA are associated with various forms of ectodermal dysplasia with immunodeficiency (EDA-ID)." (PMID 28448599, 2017).
Insulin resistance (22 papers, 2013 to 2025). Increased resistance towards insulin, that is, diminished effectiveness of insulin in reducing blood glucose levels. "Notably, IL6, NFKBIA, NFKB1, NOS3, PTPN1, PIK3R1, and STAT3 (members in the enriched WGCNA module) have been shown to alter insulin resistance." (PMID 33005175, 2020).
lymphoma (22 papers, 2003 to 2025). A malignant (clonal) proliferation of B- lymphocytes or T- lymphocytes which involves the lymph nodes, bone marrow and/or extranodal sites. "For genes in NF‐κB pathway, we found that lymphoma susceptibility of the A allele was significantly decreased in rs2233406 of NFKBIA." (PMID 37329186, 2023). "Secondly, our results showed that the rs2233406 of NFKBIA in NF‐κB pathway was significantly associated with the susceptibility of lymphoma in a variety of models (dominant, overdominant, codominant, additive, or allele models)." (PMID 37329186, 2023). "Our results also suggested that lenalidomide might relieve relapsed lymphoma with mutations in NFKBIA 202C>T (p.Q68*) and NFKBIE 433A>T (p.K145*) by targeting NF-Kappa B signaling." (PMID 34405005, 2021). "In keeping with this, CYCLON and JQ1 regulate a number of genes that encode factors of relevance to lymphoma B-cell survival, including the inhibitor of NFKB signalling, NFKBIA as well as JNK1, known to be involved in complement-mediated cytotoxicity." (PMID 23828858, 2013). "The distinctive mBL signature consisted of 58 genes, including several target genes of the NF-κB pathway (i.e., BCL2A1, FLIP, CD44, NFKBIA, BCL3, and STAT3) that are known to distinguish activated B-cell-like or germinal center B-cell-like lymphomas." (PMID 26416427, 2015).
ovarian carcinoma (21 papers, 2009 to 2024). A malignant neoplasm originating from the surface ovarian epithelium. "To assess whether overall variation within each gene was associated with ovarian cancer risk, we performed multiple logistic regression for participants with complete genotype data (N = 1,901 for NFKBIA, N = 1,930 for NFKBIB)." (PMID 19500386, 2009). "We used a case-control study to evaluate the association between single nucleotide polymorphisms (SNPs) in NFKBIA and NFKBIB (the genes encoding IκBα and IκBβ, respectively) and risk of epithelial ovarian cancer." (PMID 19500386, 2009). "In summary, single-SNP, multi-SNP, and haplotype analyses do not indicate that NFKBIA or NFKBIB harbor risk alleles for ovarian cancer." (PMID 19500386, 2009). "Because of NF-κB's central role in numerous cancer-related processes and involvement in risk of others cancers, we hypothesized that inherited variation in the genes encoding the key inhibitors IκBα and IκBβ (NFKBIA and NFKBIB, respectively) is associated with ovarian cancer risk." (PMID 19500386, 2009). "This study was designed to detect modest genetic associations with ovarian cancer risk; results suggest that common risk alleles of modest effect size may not reside in NFKBIA or NFKBIB." (PMID 19500386, 2009). "Considering the number of single-SNP tests performed and null gene-level results, we conclude that NFKBIA and NFKBIB are not likely to harbor ovarian cancer risk alleles." (PMID 19500386, 2009). "However, considering the number of single-SNP tests performed and the null gene-level results, they concluded that NFKBIA and NFKBIB were not likely to harbor any alleles associated with the risk of ovarian cancer." (PMID 25215581, 2014).
Obesity (17 papers, 2012 to 2026). Accumulation of substantial excess body fat. "NFKBIA has a critical role in the upregulation of pro-inflammatory factors and is considered a link between immunological stress and obesity." (PMID 27936208, 2016).
rheumatoid arthritis (16 papers, 2009 to 2026). A chronic, systemic autoimmune disorder characterized by inflammation in the synovial membranes and articular surfaces. "RESULTS: Integrated analysis identified 34 common targets of Er Miao San (EMS) for rheumatoid arthritis (RA) treatment, with NFKBIA, RELA, and TNF recognized as the top hub genes." (PMID 41963877, 2026). "Immune pathways were also enriched: Role of Osteoclasts in Rheumatoid Arthritis (FDR = 5.88 × 10−3; MMP12, ADAM9, NFKBIA), T-cell receptor and Interleukin-1 signaling (both FDR = 8.83 × 10−3; NFKBIA, PSME3)." (PMID 41465234, 2025).
Hyperglycemia (15 papers, 2008 to 2025). An increased concentration of glucose in the blood. "Remarkably, hyperglycaemia seemed to reduce gene expression (significantly so for NFKBIA, IL1A and CCL3), whereas hyperinsulinaemia enhanced the expression of six out of eight measured inflammatory genes." (PMID 18290856, 2008).
osteosarcoma (14 papers, 2010 to 2025). A usually aggressive malignant bone-forming mesenchymal neoplasm, predominantly affecting adolescents and young adults. "miR-301a-3p, RAB5A, and NFKBIA were abnormally expressed in osteosarcoma tissues." (PMID 36438897, 2022).
Hodgkins lymphoma (13 papers, 2009 to 2024). A heterogeneous group of malignant lymphoid neoplasms of B-cell origin characterized histologically by the presence of Hodgkin and Reed-Sternberg (HRS) cells in the vast majority of cases. "The first mutations of NFKBIA, the gene codifying for IκBα, in cancer were detected in Hodgkin lymphoma (HL), a B-cell lymphoma developed in lymph nodes, characterized by the presence of giant Reed-Sternberg (RS) cells." (PMID 34572464, 2021). "In 37.5% of patients with Hodgkin lymphoma, mutations in the NFKBIA gene in the tumor cells were detected." (PMID 27047795, 2016). "Inactivating mutations of NFKBIA have been found in Hodgkin lymphoma, and heterozygous NFKBIA deletions were reported in ~25% of GBM cases.." (PMID 24367615, 2013).
ulcerative colitis (13 papers, 2012 to 2024). An inflammatory bowel disease involving the mucosal surface of the large intestine and rectum. "Another study showed that NFKBIA is targeted by miR-126 in ulcerative colitis." (PMID 38539461, 2024). "Finally, rs696, located in the 3′ UTR of NFKBIA gene, was associated with Guillain–Barré syndrome, Behcet disease and anti-TNF response in patients with Crohn’s disease and ulcerative colitis." (PMID 38540428, 2024).
ectodermal dysplasia (11 papers, 2010 to 2025). "Moreover, mutations in NFKBIA are associated with ectodermal dysplasia, suggesting that its expression may influence reproductive performance." (PMID 40003088, 2025).
osteoarthritis (10 papers, 2016 to 2023). A noninflammatory degenerative joint disease occurring chiefly in older persons, characterized by degeneration of the articular cartilage, hypertrophy of bone at the margins and changes in the synovial membrane. "Four genes, MYC, JUN, DUSP1 and NFKBIA, were selected as potential diagnostic biomarkers in osteoarthritis." (PMID 36681837, 2023). "Among them, four genes (MYC, JUN, DUSP1 and NFKBIA) specifically expressed in immune system were identified and clinical samples revealed consistent change of these four genes in synovial tissue retrieved from patients with osteoarthritis." (PMID 36681837, 2023). "Finally, four feature genes, including MYC, JUN, DUSP1 and NFKBIA were identified, which had well predictive performance in osteoarthritis." (PMID 36681837, 2023). "MYC, JUN, DUSP1 and NFKBIA might be biomarkers and potential therapeutic targets in osteoarthritis." (PMID 36681837, 2023). "Although there was no statistical significance, the expression of NFKBIA in synovial tissues of osteoarthritis patients showed a reduced trend in comparison with that of normal controls." (PMID 36681837, 2023).
mastitis (9 papers, 2020 to 2025). Inflammation of breast tissue during lactation or postpartum due to an obstructed duct or infection. "Some of the highly connected genes in the purple module have previously been related to mastitis development including NFKBIZ, NFKBIA, CXCL2, GRO1, CXCL3, LPIN1, and DAB2." (PMID 32754201, 2020).
liver cancer (8 papers, 2019 to 2024). An epithelial or non-epithelial malignant neoplasm that arises from the liver. "It has been observed that NFKBIA expression in liver cancer tissue is lower than in normal tissue, and that negative NFKBIA expression predicts poor prognosis in individuals with primary HCC24." (PMID 38969729, 2024).
acute kidney injury (7 papers, 2018 to 2024). Sudden and sustained deterioration of the kidney function characterized by decreased glomerular filtration rate, increased serum creatinine or oliguria. "In the present study, we investigated the association of 12 polymorphisms in six inflammatory-response genes (TNF, IL6, IL10, IL18, NFKB1 and NFKBIA) with risk of acute kidney injury (AKI) in children." (PMID 30429237, 2018).
autoimmune disease (7 papers, 2011 to 2023). A disorder resulting from loss of function or tissue destruction of an organ or multiple organs, arising from humoral or cellular immune responses of the individual to their own tissue constituents. "A previous meta-analysis found that NFKBIA was closely related to autoimmune diseases and susceptibility to inflammatory diseases." (PMID 37056763, 2023).
coronary artery disease (7 papers, 2015 to 2025). "NFKBIA polymorphisms modulated the risk of coronary artery disease in the Chinese Uygur population by regulating various cytokines including interleukin-6, which is a key mediator of the inflammatory process and atherosclerotic plaque formation." (PMID 31180540, 2019). "NFKBIA is shown to be linked with coronary artery disease in the Chinese population." (PMID 40607379, 2025). "Another study also identified a series of immune cell-related genes, including FOS, DUSP1, CXCL8, and NFKBIA, which can not only differentiate between AMI and coronary heart disease (CHD) but also predict the risk of HF in AMI patients." (PMID 37965091, 2023).